Y_RNA (Y RNA )
Gene: Miscellaneous RNA gene on chromosome 7 (36,337,667 to 36,337,778, reverse strand). Ensembl gene ENSG00000201432.
Homologues: Orthologues: chimpanzee Y_RNA (94% identical), macaque Y_RNA (92% identical). Paralogues in human: RNY1 (88% identical), Y_RNA (86% identical), RNY1P11 (85% identical), Y_RNA (85% identical), Y_RNA (84% identical), Y_RNA (83% identical), Y_RNA (82% identical), Y_RNA (81% identical), Y_RNA (80% identical), RNY1P12 (79% identical), RNY1P7 (79% identical), RNY1P8 (79% identical), and 94 more.